COL6A4P2 (collagen type VI alpha 4 pseudogene 2)
Synonyms: COL6A4
Gene: Transcribed unitary pseudogene on chromosome 3 (130,212,823 to 130,273,327, forward strand). Ensembl gene ENSG00000228252.
Diseases named in the same sentence as COL6A4P2 in open-access papers:
COL6A4P2 is named in the same sentence as 3 diseases in open-access papers, as found by Europe PMC text mining. Sharing a sentence is not in itself a finding about the gene and the disease. The quoted sentences say what the papers report.
lung carcinoma (1 paper, 2021). "Distribution of COL6A4P2 polymorphisms in populations of different ages and genders and its association with risk of lung cancer." (PMID 34019596, 2021). "Distribution of genotypes of COL6A4P2 polymorphism depicting their association with lung cancer risk and its histological subtypes." (PMID 34019596, 2021). "Association between COL6A4P2 polymorphism and tumor staging of lung cancer." (PMID 34019596, 2021). "Basic information about SNPs in COL6A4P2 and association with risk of lung cancer in allele model." (PMID 34019596, 2021).
COL6A4P2 also shares sentences with these, for which no sentence is quoted: tendinitis (1 paper); tumor (1).